CASP1 (caspase 1)
Diseases named in the same sentence as CASP1 in open-access papers (continued):
Sharing a sentence is not in itself a finding about the gene and the disease.
schizophrenia (5 papers, 2023 to 2026). A major psychotic disorder characterized by abnormalities in the perception or expression of reality. "Our results show that the expressions of miR-3653-3p in the peripheral blood of patients with acute schizophrenia were lower, which was first reported in schizophrenia, and the relative expressions of caspase 1 mRNA and IL-1β mRNA were all elevated." (PMID 37946206, 2023). "Previously, differentially expressed prefrontal cortex NLRP3, Caspase 1, and IL-1β have been reported in post-mortem brains of schizophrenia patients." (PMID 37946206, 2023). "The expression of miR-3653-3p, NLRP3, caspase 1, and IL-1β in schizophrenia does show interconnection." (PMID 37946206, 2023). "The role of NLRP3, Caspase 1, and IL-1β in the pathological process of schizophrenia deserves further investigation." (PMID 37946206, 2023). "Similarly, HERV-W env upregulates NLRP3, CASP1, and GSDMD expression, promoting lactate dehydrogenase (LDH) and IL-1β release and inducing CASP1–GSDMD-dependent neuron pyroptosis in recent-onset schizophrenia." (PMID 41200560, 2025). "Furthermore, the relationship between miR-3653-3p/NLRP3/caspase 1/IL-1β and the pathogenesis of schizophrenia was further verified by in vitro and in vivo experiments." (PMID 37946206, 2023). "In the future, the relationship between miR-3653-3p and NLRP3, caspase 1, and IL-1β in patients with schizophrenia is worthy of in-depth research and further validating the potential of miR-3653-3p, NLRP3, caspase 1, and IL-1β as a stable biomarker for schizophrenia in diagnostic experiments." (PMID 37946206, 2023). "Intriguingly, NLRP3/Caspase 1/IL-1β is also involved in the classical pyroptosis pathway, in which IL-1β and IL-18 are activated, and the inflammation is amplified, which may contribute to the pathogenesis of schizophrenia." (PMID 37946206, 2023). "Conversely, other TNFSF downstream mRNAs were unchanged (BAX, BID, CASP1, CASP3, CASP8, and CASP9) in high-inflammation schizophrenia cases compared with low-inflammation controls." (PMID 41567988, 2026). "Our clinical observations revealed that the levels of CASP1, GSDMD, and IL1B were significantly elevated in the blood of patients with schizophrenia and positively correlated with HERV-W env." (PMID 39859234, 2025). "Previous research has observed significant upregulation of pyroptosis-related genes, such as CASP1, NLRP3, and IL1B, in the serum of schizophrenia patients." (PMID 39859234, 2025). "Our clinical data showed that pyroptosis-related genes, including CASP1, GSDMD, and IL1B, were significantly elevated in patients with schizophrenia and positively correlated with HERV-W env expression." (PMID 39859234, 2025). "Clinical studies have shown elevated levels of CASP1, GSDMD, and IL1B in the blood of schizophrenia patients, highlighting their role in the classical pyroptosis pathway." (PMID 39859234, 2025). "Our clinical findings indicate a strong association between HERV-W env and the pyroptosis-related genes CASP1, GSDMD, and IL1B in individuals with schizophrenia." (PMID 39859234, 2025).
schizophrenia (continued). "In this study, we discovered that HERV-W env promotes pyroptosis by increasing the expression of NLRP3, CASP1, GSDMD and IL1B, potentially representing a novel mechanism by which HERV-W env influences neuronal cell death in patients with schizophrenia." (PMID 39859234, 2025). "In this study, we found that the expression levels of pyroptosis-related genes, specifically CASP1, GSDMD (Gasdermin D), and IL1B, were significantly elevated in patients with schizophrenia compared to healthy controls." (PMID 39859234, 2025). "Moreover, our clinical data revealed that the levels of CASP1, GSDMD, and IL1B in the blood of schizophrenia patients were significantly higher than those in healthy controls, consistent with the prediction from bioinformatics analysis of GSE25673." (PMID 39859234, 2025). "Additionally, Spearman’s analysis demonstrated that HERV-W env positively correlated with CASP1 (r = 0.7156), GSDMD (r = 0.7690), and IL1B (r = 0.6172) in the blood of schizophrenia patients." (PMID 39859234, 2025). "Follow-up could be continued in the future, or a comparative study could be conducted between the untreated schizophrenia and chronic schizophrenia patients to detect the expression levels of miR-3653-3p, NLRP3, caspase 1, and IL-1β." (PMID 37946206, 2023). "Finally, we detected miR-3653-3p and NLRP3, Caspase 1 and IL-1β mRNA and explored the relationship between miR-3653-3p and NLRP3, Caspase 1, IL-1β in peripheral blood of schizophrenia; we look forward to searching for stable biomarkers of schizophrenia in peripheral blood." (PMID 37946206, 2023). "Thus, our study results also indicated that miR-3653-3p could be involved in the expression of NLRP3, caspase 1, and IL-1β, though NLRP3 was not statistically different between patients with schizophrenia and the controls." (PMID 37946206, 2023).
systemic inflammatory response syndrome (5 papers, 2011 to 2025). SIRS is a serious condition related to systemic inflammation, organ dysfunction, and organ failure. "Our results also imply the possibility that Rab39a is a potent target molecule to control the sepsis syndrome because Rab39a regulates the inflammatory responses by controlling Caspase-1 activity and autophagy induction in response to LPS stimulation." (PMID 24349490, 2013). "Although multiple studies have shown that caspase-8 can directly cleave pro-IL-1β into mature IL-1β in circumstances such as TNF-α-induced systemic inflammatory response syndrome (SIRS), mature IL-1β fragments were undetectable in caspase-1-deficient macrophages upon nigericin treatment." (PMID 41208996, 2025). "The NLR Family Pyrin Domain-Containing 3 (NLRP3) inflammasome/caspase-1/IL-1β pathway may be involved to some extent in the occurrence of systemic inflammatory response syndrome (SIRS)." (PMID 40041174, 2025). "Caspase-1 activation is constitutively present in human primary monocytes isolated from healthy volunteers, yet it is absent in patients with sepsis syndrome, as shown in the present study." (PMID 21244670, 2011).
temporal lobe epilepsy (5 papers, 2015 to 2026). A localization-related (focal) form of epilepsy characterized by recurrent seizures that arise from foci within the temporal lobe, most commonly from its mesial aspect. "In human temporal lobe epilepsy patients, Caspase 1 is often upregulated in the hippocampi of patients with temporal lobe epilepsy and silencing of Caspase 1 or NLRP1 produces neuroprotective and antiepileptic effects which is also consistent with our data." (PMID 38166692, 2024). "For instance, overexpression of caspase-1 in subicular pyramidal neurons was sufficient to induce pharmacoresistant temporal lobe epilepsy in rats." (PMID 38078329, 2023).
Ureteral obstruction (5 papers, 2021 to 2024). Obstruction of the flow of urine through the ureter. "VX-765 (belynacasan), an orally administered selective caspase 1 inhibitor, decreased the expression of fibrosis markers in mice subjected to unilateral ureteral obstruction." (PMID 38740765, 2024). "Belnacasan, a selective caspase-1 inhibitor, has shown a reduction in fibrosis formation in mice with unilateral ureteral obstruction (UUO)." (PMID 38740765, 2024). "For instance, reduced expression and maturation of IL-1β, IL-18 and caspase-1 activation and reduced tubular damage and fibrosis in an NLRP3 knockout unilateral ureteral obstruction (UUO) model was observed." (PMID 34680443, 2021).
varicocele (5 papers, 2020 to 2023). A condition characterized by the dilated tortuous veins of the spermatic cord with a marked left-sided predominance. "The mRNA levels of NLRP3, apoptosis-associated speck-like protein containing a caspase recruitment domain, and caspase-1 were evaluated by real-time polymerase chain reaction at 1, 2, 4, 8, and 12 wk after varicocele induction." (PMID 37727396, 2023). "We analyzed the mRNA expression of NLRP3, ASC, and caspase-1, the key inflammatory markers, during 1, 2, 4, 8, and 12 wk after varicocele induction in both left and right testes." (PMID 37727396, 2023). "On the contrary, in varicocele rats treated with Se, many caspase-1 positive cells were present in the periphery of the seminiferous tubules." (PMID 33525681, 2021). "In varicocele rats, a large number of caspase-1 positive cells were located in the highly damaged wall of the tubules." (PMID 33525681, 2021). "On the contrary, both Se and PDRN treatment reduced caspase-1 and IL-1β levels in testes of varicocele animals (p < 0.0001 versus varicocele)." (PMID 33525681, 2021). "In our previuos work, we showed high levels ofASC, NLRP3 and caspase 1 expression in the testis tissueof varicocele-induced rats, three months after surgery." (PMID 32112635, 2020). "In this study, we analyzed relationship of spermparameters with NLRP3, ASC, IL-18 and caspase-1 inboth control and varicocele groups." (PMID 32112635, 2020). "Although we could not detect any significant changes in the level of expression of the NLRP3 inflammasome before the 12th wk, changes were reported in NLRP3, caspase-1, and IL-1b mRNA levels 2 months after varicocele induction." (PMID 37727396, 2023). "Additionally,concentration of IL-1β was higher in varicocele versuscontrol subjects, whereas IL-18 was decreased in seminalplasma of varicocele patients and caspase-1 was notchanged." (PMID 32112635, 2020). "The testis cell pyroptosis mediated by CASP1 and CASP4 found in this study was limited to the testicular tissue of patients with SCOS, possibly caused by known factors, such as varicocele, testicular microlithiasis, and testicular hydrocele or other unknown factors." (PMID 37296437, 2023). "In varicocele animals, lower testosterone levels, testes weight, NLRP3 inflammasome, IL-1β and caspase-1 increased gene expression were demonstrated." (PMID 33525681, 2021). "In the testes of varicocele rats treated with PDRN, a reduced number of caspase-1 positive cells were located along the periphery of the tubules." (PMID 33525681, 2021). "During the 1, 2, 4, and 8 wk after varicocele induction, no significant changes were observed (p = 0.09) in the level of expression of NLRP3, ASC, and caspase-1 in both testes compared to the control group." (PMID 37727396, 2023). "In the seminiferous tubules of both operated and contralateral testes of varicocele rats treated with Se plus PDRN, very rare or no caspase-1 positive cells were demonstrated." (PMID 33525681, 2021).
viral myocarditis (5 papers, 2019 to 2024). Myocarditis that is caused by an infection with a viral agent. "Our previous study has shown that NAC inhibits CVB3 replication and alleviates viral myocarditis, and the antiviral mechanism of NAC is associated with its downregulation of caspase-1." (PMID 39339978, 2024). "For instance, miR-15 has been found to upregulate the levels of NLRP3 and caspase-1 p20, thereby promoting the activation of NLRP3 inflammasome and aggravating the inflammatory response of viral myocarditis." (PMID 38643118, 2024). "In CVB3-induced viral myocarditis, IL-37 treatment obviously weakened the upregulation of NLRP3 inflammasomes (NLRP3, ASC, and caspase-1), and the activation of NLRP3 inflammasomes as evidenced by decreased inflammatory mediators (IL-1β and IL-18)." (PMID 36418383, 2022).
acute lung injury (4 papers, 2018 to 2025). A condition of lung damage that is characterized by bilateral pulmonary infiltrates (pulmonary edema) rich in neutrophils, and in the absence of clinical heart failure. "We and others have recently linked the activation of caspase-1 and GSDM-D protein with vascular cell injury, the central component of acute lung injury (ALI/ARDS)." (PMID 30596757, 2018). "AMs, the major immunocytes regulating lung inflammation and acute lung injury (ALI), respond to invasive stimuli via pyroptosis, which is a caspase-1-dependent death pathway." (PMID 37377971, 2023).
AIDS (4 papers, 2018 to 2025). A syndrome resulting from the acquired deficiency of cellular immunity caused by the human immunodeficiency virus (HIV). "In a humanized mouse model of infection, HIV-1 protease cleavage of CARD8 in CD4+ T-cells results in caspase-1 inflammasome assembly and pyroptosis, leading to depletion of these cells, which is one of the hallmarks of disease progression in AIDS." (PMID 39883598, 2025).
Allergy (4 papers, 2018 to 2024). An allergy is an immune response or reaction to substances that are usually not harmful. "To further analyze the potential inflammasome-independent role of NLRP3 in BP allergy, we next sensitized Casp1-deficient animals in addition to C57BL/6 WT and Nlrp3-/- mice." (PMID 38933263, 2024). "When an allergy model of house dust mite allergen was exposed to MWCNTs, the allergic response was prevented through suppression of IL-1β and pro-caspase-1 in alveolar macrophages." (PMID 30372450, 2018).
atrial fibrillation (4 papers, 2019 to 2025). A disorder characterized by an electrocardiographic finding of a supraventricular arrhythmia characterized by the replacement of consistent P waves by rapid oscillations or fibrillatory waves that vary in size, shape and timing and are accompanied by an irregular ventricular response. "In summary, these findings demonstrate that diabetes promotes activation of the NLRP3 inflammasome–CASP1–galectin-3 axis within atrial tissue, contributing to the initiation of atrial fibrillation." (PMID 40649732, 2025). "Altogether, while ASC and caspase-1 represent mechanistically rational targets within the inflammasome cascade, their therapeutic exploitation in atrial fibrillation remains limited." (PMID 40649732, 2025).
cardiac arrest (4 papers, 2015 to 2020). Cessation of breathing and/or cardiac function. "We then examined whether MCC950 prevents microglial pyroptosis and the increased caspase-1 activity in activated microglia caused by cardiac arrest." (PMID 32703306, 2020). "“Cardiac arrest group” skin was associated with elevated levels of caspase-1 and IL-18." (PMID 26635801, 2015). "As illustrated, the number of pyroptotic microglia and live microglia expressing caspase-1 in the post-cardiac arrest brain tissues (hippocampus and cortex) was significantly higher than that in the sham-operated brain tissues." (PMID 32703306, 2020). "The elevated expression of NLRP3 and cleaved caspase-1 were further confirmed by immunofluorescent staining at 12 h after cardiac arrest, along with ASC, another key molecule involved in the assembly of inflammasome." (PMID 32703306, 2020). "As shown by the co-immunoprecipitation, pairwise interactions among NLRP3, ASC, and caspase-1 were observed in both the hippocampus and cortex tissues at 12 h after cardiac arrest." (PMID 32703306, 2020). "Nonsurvivors at 30 days had significantly lower mRNA levels of TLR2, IRAK3, IRAK4, NLRP3 and CASP1 in the late phase following cardiac arrest." (PMID 27260481, 2016). "In “cardiac arrest group” muscle, IL-18 levels were also markedly increased; however, caspase-1 levels were lower than in “injury group” muscle." (PMID 26635801, 2015). "As expected, targeting caspase-1 by Ac-YVAD-cmk substantially reduced the number of pyroptotic cells and live cells expressing caspase-1 in all microglia population (CD45low CD11b+ and CD45int CD11b+) as well as in the CD45int CD11b+ population after cardiac arrest." (PMID 32703306, 2020). "Consistent with this hypothesis, our data demonstrate that there is indeed intensive pyroptosis and increased caspase-1 activity in the activated microglia population after cardiac arrest, along with elevated levels of IL-1β and IL-18." (PMID 32703306, 2020). "We then assessed whether the suppression of microglia pyroptosis by targeting caspase-1 with Ac-YVAD-cmk ameliorated neurological injury in a rat model of cardiac arrest." (PMID 32703306, 2020). "However, the protein level of cleaved caspase-1, namely the active form of capase-1, was increased at 6 to 24 h in the post-cardiac arrest brain, indicating that the pro-caspase-1 underwent autocatalysis and activation after the cardiac arrest." (PMID 32703306, 2020). "We next detected whether the inhibition of caspase-1 by Ac-YVAD-cmk suppressed microglia pyroptosis and the caspase-1 activity in activated microglia caused by cardiac arrest." (PMID 32703306, 2020). "Notably, IL-1α and IL-18, along with caspase-1, were greatly elevated in the skin following cardiac arrest, consistent with differential inflammasome activation." (PMID 26635801, 2015). "Cardiac arrest greatly elevates IL-1α, IL-18, and caspase-1 in the skin." (PMID 26635801, 2015). "Here, we revealed that NLRP3 and ASC were upregulated in the post-cardiac arrest brain with biological interaction, and both NLRP3 and ASC had interaction with caspase-1, which represent the intracellular activation of NLRP3 inflammasome." (PMID 32703306, 2020). "To further verify the role of NLRP3 inflammasome in mediating post-cardiac arrest microglial pyroptosis and its consequential brain injury, we used a selective inhibitor Ac-YVAD-cmk to target caspase-1, the canonical executor of pyroptosis." (PMID 32703306, 2020). "Taken together, these findings imply that cardiac arrest activates the assembly of NLRP3 inflammasome in microglia, which leads to the self-cleavage of caspase-1 and triggers microglial pyroptosis." (PMID 32703306, 2020). "The mRNA level of caspase-1 and the protein level of pro-caspase-1 were not altered for the rats undergoing cardiac arrest compared to sham operation." (PMID 32703306, 2020).
cardiac arrest (continued). "Thus, targeting caspase-1 by Ac-YVAD-cmk prevents microglial pyroptosis and consequential neuroinflammation after cardiac arrest." (PMID 32703306, 2020). "We did not observe a change in monocyte CASP1 mRNA expression in patients who had experienced cardiac arrest compared to patients with CAD." (PMID 27260481, 2016).
corneal infection (4 papers, 2018 to 2024). A viral or bacterial infectious process affecting the cornea. "Since induction of inflammasomes triggers Caspase-1 activation, we next determined whether corneal infection with virulent HSV-1 strains would enhance the expression levels of one or several of the five major inflammasomes: NLRP3, NLRP6, NLRP12, IFI16/p204, and AIM2." (PMID 31367214, 2019).